FLG (filaggrin)
Diseases named in the same sentence as FLG in open-access papers (continued):
Sharing a sentence is not in itself a finding about the gene and the disease.
psoriasis (continued). "It was observed there was an increase in the content of both involucrin and filaggrin, which are usually disturbed in psoriasis patients, in addition to skin irritation studies which proved that no adverse effects or itching were observed upon using VCO." (PMID 36986611, 2023). "FLG is a key component of the cuticle, and its genetic defects are believed to be involved in the development of psoriasis and AD and other IgE sensitization." (PMID 36314037, 2022). "PPPs altered the mRNA expressions of the inflammatory cytokines (TNF-α, IL-6, and IL-1β) and improved the expressions of AQP3 and FLG in psoriasis-like mouse skin." (PMID 35153762, 2021). "Decreased levels of AQP3 and FLG are commonly seen in skin barrier disruption, which appears to be a key player in epidermal biology in psoriasis." (PMID 35153762, 2021). "The changes in epidermal morphology were accompanied by lowered protein expression levels of the terminal differentiation protein FLG, while psoriasis markers hBD2 and SKALP were upregulated." (PMID 28928444, 2017). "Filaggrin was only expressed in a patchy fashion in psoriasis lesions, whereas it formed a continuous layer at the transition from the stratum granulosum to stratum corneum in both non lesional psoriatic and normal skin." (PMID 21364982, 2011). "Furthermore, treatment with PPS induces an increase in filaggrin, a protein downregulated in psoriasis that plays a crucial role in the formation of the skin barrier." (PMID 41226468, 2025). "The primary susceptibility gene for psoriasis is HLA-Cw*0602 located on the PSORS1 locus (6p21), while for AD, one of the most significant genetic risks is associated with null mutations in the filaggrin gene (FLG)." (PMID 41517378, 2025). "Current genome-wide comparative analyses have confirmed the presence of FLG gene mutations in the epidermal differentiation complex on chromosome 1q21.3 in AD but not in psoriasis." (PMID 40920623, 2025). "On the contrary, previous data suggested that mutations in Filaggrin were not involved in genetic predisposition to psoriasis." (PMID 38907248, 2024). "In addition, there was a significant gradual reduction of Filaggrin in dermal blood vessels and inflammatory cells from normal to peri-lesional and psoriasis skin." (PMID 38907248, 2024). "Taken together, decreased Filaggrin in psoriatic lesion may suggest its involvement in psoriasis pathogenesis." (PMID 38907248, 2024). "To assess the effects of the drug on improving disease phenotype, we examined the expression of the epithelial markers filaggrin, loricrin and elafin in the epidermis of cytokine-induced psoriasis models and AD models before and after tofacitinib treatment by immunohistology." (PMID 38251799, 2024). "In addition, increased expression of Filaggrin was detected after treatment of psoriasis, followed by the down-regulation of proinflammatory factors, improvement of the skin barrier and remission." (PMID 38907248, 2024). "Furthermore, vitamin D contributes to skin barrier integrity by upregulating proteins like filaggrin and involucrin, addressing a common deficit in psoriasis." (PMID 39796035, 2024). "Interestingly, integrated TH1 cells were able to change the expression of epidermal barrier proteins as seen in patients with psoriasis, as evidenced by reduced expression of filaggrin and increased expression of elafin." (PMID 38251799, 2024). "Since lncRNA uc.291 can dislodge ACTL6A-chromatin binding on the EDC locus, allowing the activation of transcription of differentiation genes residing at the EDC locus, including filaggrin and loricrin, we decided to determine their expression in patients with psoriasis skin and in healthy donors." (PMID 38041107, 2023). "However, the lesion skin of psoriasis patients exhibits epidermal dysfunction and diminished expression of filaggrin, likely influenced by cytokines such as IL-2." (PMID 37795084, 2023).
psoriasis (continued). "Furthermore, TNF-α, a key cytokine in the pathogenesis of psoriasis, reportedly decreased filaggrin and loricrin expression in human keratinocytes." (PMID 37834081, 2023). "Furthermore, immunohistochemical staining of normal and psoriatic lesional skin biopsies reveals that Filaggrin expression is drastically reduced at the protein level in psoriasis." (PMID 38041107, 2023). "Although symptoms of psoriasis are similar to those of AD, mutations in filaggrin are not causative for psoriasis." (PMID 35163390, 2022). "To assess whether FZHFZY influences epidermal differentiation in the skin of mice with IMQ-induced psoriasis, we detected the expression of loricrin, filaggrin, involucrin, keratin 5, keratin 14 and keratin 15 in the skin by RT-PCR and western blotting." (PMID 34456715, 2021). "Thus, it remains to be seen if Filaggrin is involved in psoriasis pathogenesis." (PMID 38907248, 2024). "Additionally, the downregulated expression of FLG has been observed in some psoriasis patients even when identified FLG gene mutations are absent." (PMID 38606161, 2024). "Therefore, recovery of filaggrin and involucrin, which are reduced in AD conditions, may help in relieving symptoms such as skin dryness, erythema, psoriasis, and desquamation." (PMID 34204204, 2021). "Slides cut from paraffin blocks of 30 psoriasis cases and 30 control subjects were stained with OVOL1 and Filaggrin." (PMID 38907248, 2024). "We performed CODEX analysis for the markers filaggrin, elafin, loricrin, Ki-67 and inducible nitric oxide synthase (NOS2) of the TH17-induced psoriasis model (‘TH17’) and TH2-induced AD model (‘TH2’) and compared the results to the untreated control group." (PMID 38251799, 2024). "Therefore, Filaggrin could have a role in progression of psoriasis." (PMID 38907248, 2024). "The authors also found that many psoriasis-specific DEPts were fragments of four proteins, namely fibrinogen α/FGA, filaggrin/FLG, thymosin beta-4/TMSB4X, and FLJ55606 (highly similar to alpha-2-HS-glycoprotein)." (PMID 35327421, 2022). "Decreased levels of FLG and LOR mRNA have already been demonstrated in the skin of CTCL and psoriasis patients, which confirms that skin barrier dysfunction is not specific to AD pathogenesis." (PMID 32213830, 2020). "Moreover, decreased expression of filaggrin in the lesional skin of psoriasis due to secreted cytokines including IL-4, IL-13, IL-17, and TNF-α might increase the risk of skin cancer by increasing UV sensitivity of patients with psoriasis." (PMID 32987907, 2020). "Taken together, it can be suggested that inhibition of OVOL1 could suppress Filaggrin function and discovering OVOL1 agonists may be beneficial in psoriasis treatment." (PMID 38907248, 2024). "The relation between Filaggrin and OVOL1 in psoriasis is still unclear." (PMID 38907248, 2024). "Also, treatment of psoriasis patients with etanercept, an anti-TNF-α antibody, reversed filaggrin and loricrin downregulation." (PMID 37834081, 2023). "In our study, there is downregulated expression of loricrin, filaggrin and involucrin, but elevated expression of keratin 5, keratin 14 and keratin 15 in IL-17A/IL-22/IFN-γ/TNF-α–induced HaCaT cells and in mice with IMQ-induced psoriasis." (PMID 34456715, 2021). "Overall, these results indicated that PPPs ameliorated the symptoms of psoriasis through inhibition of the inflammatory cytokines by suppressing the NF-κB and STAT3 signaling pathways and improved skin barrier protection via enhancing AQP3 and FLG." (PMID 35153762, 2021). "The dysregulated expression of FLG, FLG2, LOR, and IVL is known to be normalized by specific biologic treatments, for example, blockade of interleukin-4 (IL-4) and IL-13 in AD or blockade of IL-17A in psoriasis." (PMID 32751111, 2020). "Because of the maintenance of granular layer in psoriasis-like mouse skin, filaggrin expression was not altered in our model." (PMID 26355594, 2015).
psoriasis (continued). "Another difference can be the reduced filaggrin expression in human psoriasis but not in experimental psoriasis." (PMID 26355594, 2015). "The active ingredients of the three tea alcoholic extracts could modulate multiple signaling pathways through a variety of target proteins such as TNF-α, IL-17, FLG, Cytokeratin 17, IL-23, STAT3, FLG, IFN-γ, IL-22, etc., and thus attenuate or inhibit psoriasis." (PMID 38542915, 2024). "Indeed, OVOL1 controls the expression of FLG and a recent study revealed that lipid metabolism is the most altered metabolic pathway, with the notable up-regulation of PPARδ, in OVOL1 knock-out mice treated with imiquimod to induce psoriasis-like inflammation." (PMID 35216234, 2022). "In addition, PPPs significantly suppressed the NF-κB and STAT3 pathways and accentuated the expressions of AQP3 and FLG when compared to mice with IMQ-elicited psoriasis without treatment." (PMID 35153762, 2021). "Interestingly, TNFα was also found to inhibit the expression of FLG and LOR by keratinocytes, and treatment of psoriatic patients with TNFα antagonists restored normal expression of FLG and LOR, in correlation with changes in psoriasis area and severity index." (PMID 25010647, 2014). "Because of the thinning or disappearance of the granular layer at psoriasis lesions, the spinous layer may prematurely express the products (such as fatty acid-binding protein, filaggrin, corneodesmosin, glutaminase, involucrin, and loricrin) normally expressed in the granular layer." (PMID 33967781, 2021). "No tendency for divergent gene expression of FLG, FLG2, IVL, LOR or HRNR in GATA3 silenced cells when compared to control cells was visible under psoriasis-like conditions." (PMID 28928464, 2017). "The results show that the expression of Involucrin and Filaggrin in the epidermis of let-7bTG mice are not significantly different in normal skin, whereas we observed decreased expression of let-7b in the IMQ-induced psoriasis mouse model." (PMID 30219085, 2018).
ichthyosis vulgaris (68 papers, 2008 to 2026). The most common form of ichthyosis. "Based on this background, our objective was to study genetic variants in the FLG gene and their associations in patients with a clinical diagnosis of ichthyosis vulgaris." (PMID 40282340, 2025). "Ichthyosis vulgaris is the most common form and is characterized by filaggrin null mutations causing a depletion of filaggrin which plays a role in stratum corneum integrity." (PMID 40958829, 2025). "Our objective was to study the genetic variants in the FLG gene and their associations in patients with ichthyosis vulgaris." (PMID 40282340, 2025). "The link between filaggrin deficiency and dry skin, altered pH, atopic and contact dermatitis, and ichthyosis vulgaris is also well-known." (PMID 38862781, 2024). "Ichthyosis vulgaris is caused by mutations in the filaggrin gene, resulting in defective epidermal barrier function and increased keratin production as a compensatory mechanism for barrier disruption." (PMID 39677226, 2024). "Making up more than 95% cases of ichthyosis, ichthyosis vulgaris is caused by heterozygous loss‐of‐function mutation of the filaggrin gene, raising the fragility and permeability of the stratum corneum." (PMID 36751330, 2023). "Ichthyosis vulgaris is caused by heterozygous loss‐of‐function mutations in the FLG5 which result in absolute or relative deficiency of filaggrin, disrupting the epidermal barrier." (PMID 36751330, 2023). "FLG mutations cause ichthyosis vulgaris in both Caucasian and Asian populations, but they tend to be population specific with different and sometimes mutually exclusive mutations between these groups." (PMID 36751330, 2023). "Ichthyosis vulgaris results from an autosomal dominant mutation in the filaggrin gene, and lamellar ichthyosis results from mutations in transglutaminase-1, the major cross-linking enzyme in the stratum corneum." (PMID 38203406, 2023). "Mutations in the FLG (Filaggrin) gene were described in a heterozygous state in patients with Ichthyosis vulgaris (OMIM:146700) and a susceptibility to atopic dermatitis type 2 (OMIM: 605803)." (PMID 36076978, 2022). "Inherited mutations and loss-of-function in the filaggrin gene (FLG) was shown to cause moderate to severe ichthyosis vulgaris." (PMID 35055292, 2022). "Based on the mild phenotypes and high prevalence of common ichthyoses, we suspected that the diagnosis for the two patients was ichthyosis vulgaris caused by FLG mutations or recessive X-linked ichthyosis associated with STS (steroid sulfatase) deletions." (PMID 36332686, 2022). "In contrast, ichthyosis vulgaris (IV) is caused by filaggrin deficiency due to semi-dominant loss-of-function mutations of filaggrin (FLG) gene." (PMID 30021537, 2018). "The most common form of this disorder in humans is ichthyosis vulgaris caused by variants in the filaggrin gene." (PMID 28249031, 2017). "In 2006, the McLean group identified the first loss‐of‐function mutations in the filaggrin gene (FLG) as the cause of the common monogenic genodermatosis ichthyosis vulgaris (IV)." (PMID 27667308, 2016). "Filaggrin (FLG) loss-of-function is of great significance for barrier impairment in AD and ichthyosis vulgaris (IV), which is commonly associated with AD." (PMID 22164253, 2011). "As FLG is an important skin barrier protein and mutations of the human FLG gene are associated with ichthyosis vulgaris and atopic dermatitis, we investigated FLG-interacting proteins in the manatee, which has retained FLG, and the dugong, which has lost the C-terminal portion of FLG." (PMID 38653760, 2024). "Ichthyosis vulgaris is an inherited skin disease due to loss of function mutations in FLG gene." (PMID 36751330, 2023). "Loss-of-function mutations inFLG, encoding filaggrin, cause the common Mendelian disorder of keratinization, ichthyosis vulgaris (OMIM # 146700).FLG null mutations are also strongly associated with increased risk of atopic eczema and multiple other atopic traits." (PMID 31641698, 2019).
ichthyosis vulgaris (continued). "Additional samples were collected from the forearms of subjects with ichthyosis vulgaris (filaggrin (FLG) deficiency), recessive X-linked ichthyosis (steroid sulfatase (STS) deficiency) and autosomal recessive congenital ichthyosis type lamellar ichthyosis (transglutaminase 1 (TGM1) deficiency)." (PMID 24130705, 2013). "Our early data suggest that NMF levels correlate with FLG-null allele status and might therefore directly contribute to the dry skin phenotype seen in both patients with ichthyosis vulgaris and those with AD." (PMID 20621340, 2010). "Moreover, the discovery of LOF mutations in filaggrin was shown to cause ichthyosis vulgaris." (PMID 40225445, 2025). "However, the inter-disease comparison with ichthyosis vulgaris, which is mostly accompanied by FLG mutations, challenges this hypothesis." (PMID 31973112, 2020). "Furthermore, the comparison with ichthyosis vulgaris (IV), which is regularly accompanied by FLG mutations, seems to argue against the outside-in hypothesis as no excessive inflammation is seen in these patients." (PMID 31973112, 2020). "Genetic epidemiological studies have shown that FLG null mutations are significantly associated with palmar hyperlinearity, keratosis pilaris, fine scaling and self-reported ‘dry skin’,16 each of which may be features of ichthyosis vulgaris." (PMID 19681860, 2009). "FLG defects lead to ichthyosis vulgaris (IV), an autosomal semidominant condition with incomplete penetrance (83–96%) and variable expressivity." (PMID 39501396, 2024). "The most common form of ichthyoses is ichthyosis vulgaris (IV) ([OMIM] #146,700), which can be inherited as autosomal semi-dominant mutation in the filaggrin gene (FLG)." (PMID 37872553, 2023). "Originally discovered as homozygous and compound heterozygous individuals with ichthyosis vulgaris, loss-of-function (LOF) mutations in the FLG gene encoding filament aggregating protein (filaggrin) have been associated with early and severe atopy." (PMID 35572516, 2022). "The most common inherited ichthyosis, ichthyosis vulgaris (IV), affects around 1 in 100–250 of the northern European white population and has a complex genetic aetiology often involving the filaggrin (FLG) gene." (PMID 35104372, 2022). "Ichthyosis vulgaris is the most common form of ichthyosis in humans and caused by genetic variants in the FLG gene encoding filaggrin." (PMID 28249031, 2017). "Ichthyosis vulgaris (IV; OMIM: # 146700) is the most common type of hereditary ichthyosis related to the filaggrin gene (FLG; OMIM: # 135940), followed by the X-linked recessive ichthyosis (XLI; OMIM: 308100) which is related to the steroid sulfatase gene (STS; OMIM: # 300747)." (PMID 40282340, 2025). "FLG insufficiency or absence leads to skin disorders such as AD and ichthyosis vulgaris." (PMID 39107974, 2024). "Homozygous FLG mutation carriers have a complete absence of filaggrin expression which presents as a stable skin phenotype with chronic presence of ichthyosis vulgaris features." (PMID 36751330, 2023). "Ichthyosis vulgaris (IV, OMIM #146700) is the most frequent genetic disorder of ichthyosis caused by filaggrin deficiency due to semi-dominant loss-of-function mutations of filaggrin (FLG) gene, which affects around 1 in 250 people." (PMID 30021537, 2018). "However, FLG mutations have shown in up to 10% of non-atopic subjects in an Irish cohort, as well as in patients with ichthyosis vulgaris without AD, thus suggesting that other factors, in addition to FLG, must play a role in the pathogenesis of this complex disease." (PMID 29056696, 2017). "These are characteristic features of ichthyosis vulgaris but their pathogenesis has not yet been explained as a direct result of filaggrin haploinsufficiency." (PMID 31641698, 2019).
ichthyosis vulgaris (continued). "Previous studies reported that the number of keratohyalin granules and filaggrin expression were reduced or absent in the skin of patients with ichthyosis vulgaris; therefore, the number of keratohyalin granules in the stratum granulosum reflect filaggrin production levels." (PMID 36613524, 2022).